IGF1 (insulin like growth factor 1)
Diseases named in the same sentence as IGF1 in open-access papers (continued):
Sharing a sentence is not in itself a finding about the gene and the disease.
sarcoma (36 papers, 2008 to 2025). A usually aggressive malignant neoplasm of the soft tissue or bone. "Generation and genetic characterization of novel patient-derived CIC-DUX4 sarcoma xenografts and cell lines successfully highlighted the importance of the insulin-like growth factor 1 (IGF1)/IGF1 receptor (IGF1R) pathway in this tumor." (PMID 36358827, 2022). "Lumican, a class II SLRP, can likewise interact with the IGF-1/IGF-IR signaling pathway to regulate sarcoma growth." (PMID 34069554, 2021). "A large body of preclinical and early clinical data suggested that IGF1 and 2 might play an important role in the initiation and progression of a variety of cancers, including pediatric sarcomas." (PMID 26301204, 2015). "Though a causative relationship is unlikely between the peptide and ARMS due to the brief time course between teduglutide therapy and sarcoma diagnosis, neoplastic growth may have been accelerated by the GLP-2 analog, causing release of IGF-1." (PMID 26266067, 2015). "However, Eph and IGF1 signaling pathways cross-talk to regulate bone and skeletal muscle cells function and EphA2 and EphB4 exert oncogenic effects in different types of sarcomas, supporting the rationale for targeting Eph-dependent pathways in those tumors." (PMID 34440844, 2021). "We chose bFGF and EGF, both widely used in organoid protocols, and IGF1, as the IGF1R pathway plays a crucial role in EwS and other sarcoma entities." (PMID 40841513, 2025). "The mRNA levels of IGF1 and IGF2 were enhanced, but the expression of IGF1R was unaltered in sarcoma, indicating that tumor proliferation might be promoted by an increased effect of IGF1 and IGF2." (PMID 38338920, 2024). "Also, the insulin receptor involves metabolic regulation and forms a hybrid receptor with IGF1R for IGF1, the latter together with IGF2, to promote the proliferation of sarcoma cells." (PMID 38338920, 2024). "Nevertheless, the pathognomonic NAB2–STAT6 oncogenic fusion that induces IGF-1 overexpression and angiogenesis in the tumor microenvironment might help considering SFT as a targetable sarcoma." (PMID 35205812, 2022). "However, together with IGF1R it forms a hybrid receptor for IGF1, latter together with IGF2 is thought to have a key role in driving the proliferation and survival of sarcoma cells." (PMID 25496518, 2014). "Levels of IL-1β, IL-4, IL-6, CXCL5, CXCL12, CXCL14, MIF, IGF-1, TGFβ-1, and CCL21 were increased in one or more sarcoma cohorts compared with controls, and levels of IL-15 and IL-16 were significantly lower in one or more sarcoma cohorts compared to healthy controls." (PMID 41008853, 2025). "There are no doubts that IGF system is important for the pathogenesis and progression of sarcomas: cells produce ligands and express the receptors creating a complex network of autocrine stimulations that may sustain tumor growth based either on IGF1/IGF1R or IGF2/IR axis." (PMID 24391834, 2013).
anemia (35 papers, 2009 to 2025). A reduction in the number of red blood cells, the amount of hemoglobin, and/or the volume of packed red blood cells. "Anemia was associated with hypocortisolism (p= 0.027) and growth hormone deficiency (IGF-1) in the NFA group (p= 0.009)." (PMID 40621322, 2025). "Choi and Kim reported that both iron deficiency and anemia were 3–5 times more common in humans with low serum IGF-1 content." (PMID 38002958, 2023). "In summary, we found that low serum IGF-1 levels were independently associated with anemia and lower hemoglobin levels in patients undergoing MHD." (PMID 37403637, 2023). "Anemia associated with reduced IGF-1 concentrations was attributed to its direct effect on erythroid precursor cell proliferation." (PMID 38002958, 2023). "Our associations of lower IGF-1 with increased odds of anemia, increased odds of low serum iron, and elevated sTfR, provide evidence that energy deficits contributed to anemia and low iron status in our MINDI cohort." (PMID 36079755, 2022). "In conclusion, rs35767 TT allele carriers exhibited significantly higher concentrations of Hb, and lower risk of anemia compared with C allele carriers supporting the idea that IGF-1 plays a role in erythropoiesis homeostasis." (PMID 28415730, 2017). "In this study, we evaluated the association of the functional polymorphism rs35767 near IGF1 with Hb concentration and anemia in a large cohort of well-characterized adult White Europeans." (PMID 28415730, 2017). "Another limitation of the present study is the cross-sectional design, making causal interpretations of associations between the rs35767 polymorphism near IGF1 and anemia risk difficult." (PMID 28415730, 2017). "In female adolescents, aged 14 to 17 yr, low IGF-1 concentrations were associated with a greater incidence of iron deficiency anemia." (PMID 26779261, 2015). "Low IGF-1 has been especially associated with anemia in the pediatric population and in a wide range of disorders." (PMID 26779261, 2015). "In these subjects, the correction of anemia was associated with a significant increase in IGF-1 levels." (PMID 26779261, 2015). "After adjusting for confounding factors in different models, the nine-model multivariate binary logistic regression analyses also confirmed that lower serum IGF-1 levels and serum IGF-1 < 197.03 ng/ml were both independently associated with anemia in patients undergoing MHD." (PMID 37403637, 2023). "Other potential mechanisms by which the considered anti-hypertensive drugs may cause anemia are the serum reduction of specific cytokines, such as interleukin-12, and/or of insulin-like growth factor-1, which physiologically stimulate erythropoiesis." (PMID 31521117, 2019). "We found that, individuals carrying the TT genotype, which is associated with higher circulating IGF-1 levels, exhibited significantly higher levels of haemoglobin concentration, and lower risk of having anemia as compared with carriers of the CT or CC genotype." (PMID 28415730, 2017). "Observational studies carried out in pre-pubertal or early pubertal boys, nondiabetic adults, older (aged >65years), and elderly individuals (aged >70 years) have consistently shown that IGF-1 plasma levels associated with hemoglobin (Hb) concentration and anemia." (PMID 28415730, 2017). "The present data, coupled with the findings of previous observational studies showing an association between low IGF-1 concentration and anemia, support the idea that IGF-1 could be an important regulator of hemoglobin concentration in adults." (PMID 28415730, 2017). "IGF-1 has been hypothesized as cause of anemia under pathological conditions including a wide range of anemic disorders in observational studies." (PMID 26779261, 2015). "Moreover, both higher IGF-1 and vitamin A were associated with lower odds of anemia." (PMID 36079755, 2022). "Thus, the association between IGF-1 genotype and anemia can give an unconfounded test of whether IGF-1 levels causally influence outcomes." (PMID 28415730, 2017).
anemia (continued). "Thus, an increase of anti-inflammatory action of IGF-1 may account for the lower risk of anemia observed in subjects carrying the TT genotype." (PMID 28415730, 2017). "Experimental studies suggest that anabolic hormones such as testosterone, IGF-1, and thyroid hormones are able to increase erythroid mass, erythropoietin synthesis, and iron bioavailability, underlining a potential role of multiple hormonal changes in the anemia of aging." (PMID 26779261, 2015). "In NFA with low IGF-1, 15 (28.8%) had anemia, while in the remainder of the group, the frequency of anemia was significantly lower, with 4 (7.4%) cases." (PMID 40621322, 2025). "Iron deficiency anaemia is also associated with reduced release of insulin-like growth factor-1 (IGF-1), although it is less clear if this is due to anaemia or to iron deficiency per se." (PMID 37029208, 2023). "Results of multivariate binary logistic regression analyses of anemia (dependent variable) according to related IGF-1 indicators (independent variables)." (PMID 37403637, 2023). "Anaemia, inflammation, insulin-like growth factor-1 (IGF-1), dehydroepiandrosterone-sulphate (DHEA-S), haemoglobin A1c (HbA1c), micronutrients, adiposity and fine-motor speed were associated with a non-linear increase in frailty." (PMID 30445966, 2018). "Zinc supplementation in pregnant women with anemia resulted in an increase in insulin-like growth factor-1 (IGF-1), which was correlated with an increase in Hb levels and RBCs." (PMID 30231592, 2018). "Data were especially focused on the erythropoietic properties of a single anabolic agent (T, IGF-1, thyroid hormones, or estradiol), with limited evidence existing on the contribution of multiple anabolic pathways in the pathogenesis of anemia." (PMID 26779261, 2015). "More interestingly, the correction of anemia by blood transfusion in subjects affected by β-thalassemia and failure to thrive rapidly leads to an improvement in the GH-mediated IGF-1 and IGFBP-3 secretion." (PMID 26779261, 2015). "Irbesartan may contribute to anemia through direct inhibition of erythropoietin or insulin-like growth factor-1 production, or indirectly by improving renal perfusion and subsequently reducing oxygen consumption." (PMID 39635439, 2024). "The relationship between serum insulin-like growth factor-1 (IGF-1) levels and anemia in patients undergoing maintenance hemodialysis (MHD) remains unclear." (PMID 37403637, 2023). "Patients were divided into a group without anemia (hemoglobin ≥110 g/L) and a group with anemia (hemoglobin <110 g/L), and multivariable linear and binary logistic regression analyses were performed to study the relationship between the levels of serum IGF-1 and anemia." (PMID 37403637, 2023). "Others have observed an association between low IGF-1 with anemia in adults, which authors explained by the role of IGF-1 in promoting RBC growth and differentiation, or by a higher IGF-1 reducing concentrations of pro-inflammatory cytokines that would block erythropoiesis." (PMID 36079755, 2022). "Additionally, an intervention study demonstrated that short-term treatment with iron in children with anemia significantly increased circulating IGF-1 concentrations." (PMID 32746834, 2020). "IGF-1 might also influence the hematopoietic process and the development of anemia by modulating inflammation." (PMID 26779261, 2015). "In men, but not in women, there is also a negative and independent association between IGF-1 and anemia." (PMID 26779261, 2015). "Based on the existing evidence linking low IGF-1 levels and anemia in other populations, it could be speculated that a reduction in IGF-1 levels with aging might contribute to anemia." (PMID 26779261, 2015). "Finally, several trials were designed in order to address the effect of EPO replacement therapy on anemia and IGF-1." (PMID 26779261, 2015).
anemia (continued). "Thus, we performed an accurate review of the literature using PubMed until March 2015, by selecting the observational human studies investigating the hormonal contribution (Testosterone, IGF-1, and thyroid Hormones) to anemia older subjects of both sexes." (PMID 26779261, 2015). "In humans, IGF-1 has been hypothesized as a mediator of anemia under physiological and pathological conditions." (PMID 26779261, 2015). "Lower IGF-1 reported in serum of young children with anemia induced during P. falciparum infection, and speculated to be a reason for reduced hematopoiesis during malaria, thus leading to anemia." (PMID 39492784, 2024). "First, it had a cross-sectional design; thus, a causal relationship between serum IGF-1 levels and anemia could not be determined." (PMID 37403637, 2023). "We observed that lower levels of serum IGF-1 (odds ratio [OR] = 0.99, 95% confidence interval [CI] = 0.99–1.00, p = 0.010), serum IGF-1 < 197.03 ng/mL (OR = 0.36, 95% CI = 0.17–0.75) p = 0.007), and serum triglycerides (OR = 0.77, 95% CI = 0.59–0.99, p = 0.044) were related to anemia." (PMID 37403637, 2023). "Furthermore, serum IGF-1 and hemoglobin levels should be repeatedly measured to confirm the associations between the two to provide a theoretical basis for prospective and interventional studies on the treatment of IGF-1 in patients undergoing MHD with anemia." (PMID 37403637, 2023). "According to the results of the multivariate analysis, the variables most strongly associated with severe undernutrition were untreated water supply, anaemia, low HDL and low IGF-1." (PMID 21317999, 2010). "In prolactinomas, anemia did not diverge between patients who had or did not have low IGF-1 (p=0.127)." (PMID 40621322, 2025). "Compared to patients without anemia, patients with anemia had lower serum IGF-1 and triglyceride levels and higher intravenous iron supplementation on dialysis (all p < 0.05)." (PMID 37403637, 2023). "Our findings demonstrate a positive correlation between serum albumin, prealbumin, and IGF-1 levels, indicating that the impact of IGF-1 on nutrition may also play a role in anemia." (PMID 37403637, 2023). "Compared with patients without anemia, patients with anemia had higher levels of intravenous iron supplementation (p = 0.047) and lower levels of serum IGF-1 (p = 0.007) and serum triglycerides (p = 0.008)." (PMID 37403637, 2023). "If we assume that IGF-1 plays an anti-inflammatory effect, decreased IGF-1 concentrations may account for the increased levels of inflammatory molecules, which are known to negatively affect EPO secretion and red cell precursor survival, ultimately resulting in anemia." (PMID 26779261, 2015). "Laboratory investigations showed no abnormalities (especially no anemia or signs of HPA-axis suppression and normal kidney function, liver tests, calcium, phosphate, vitamin D, thyroid function and insulin-like growth factor-1 (IGF-1))." (PMID 39201886, 2024).
cardiomyopathy (35 papers, 2009 to 2025). A disease of the heart muscle or myocardium proper. "By upregulating the IGF1-PI3K-Akt pathway, IGF-1 tends to show cardioprotective effects, improves cardiomyopathy, and modulates the cellular processes implicated in short-term ventricular remodeling of the infarcted myocardium." (PMID 35127852, 2021). "The higher number of cKit+/CD45− CPC in IGF1-treated obese mice compared with controls is associated to a significant improvement of the cardiomyopathy provoked by Western diet-induced obesity." (PMID 35008660, 2021). "This underlines the beneficial effect on cardiomyopathy of time elapsed with normal (or even only reduced) IGF1 levels." (PMID 26429918, 2015). "Collectively, these observations suggest that excessive cardiac GH/IGF1 signaling contributes toward cardiomyopathy following genetic disruption of the cardiomyocyte circadian clock." (PMID 35250583, 2022). "Collectively, these findings suggest that augmented cardiac GH/IGF1 signaling following genetic disruption of the cardiomyocyte circadian clock likely contributes towards cardiomyopathy development." (PMID 35250583, 2022). "Collectively, these data suggest that excessive GH/IGF1 signaling in the heart contributes towards age-onset cardiomyopathy following disruption of the cardiomyocyte circadian clock." (PMID 35250583, 2022). "Activation of the insulin/IGF-1 signaling cascade is markedly inhibited in the hearts of wild-type mice following induction of cardiomyopathy." (PMID 21084725, 2010). "Early studies focused on the protective effect of recombinant GH and insulin-like growth factor-1 (IGF-1) in cardiomyopathy, including ischemic cardiomyopathy, dilated cardiomyopathy (DCM), and tachycardia induced cardiomyopathy." (PMID 21286280, 2010). "The present results show that the expression of IGF-1 is increased in 2 models of cardiomyopathy with markedly different hypertrophic responses." (PMID 19818143, 2009). "However, in the long term, GH/IGF-1 can lead to diastolic dysfunction, systolic dysfunction, and eventually full-blown cardiomyopathy." (PMID 41589173, 2025). "Meanwhile, some studies have reported that IGF-1 treatment could effectively improve cardiac function and the survival rate in animal models of cardiomyopathy." (PMID 35282347, 2022). "Moreover, adverse cardiac remodeling and cardiomyopathy development was only partially attenuated, indicating that GH/IGF1-independent mechanisms also contribute towards cardiac pathology in CBK mice." (PMID 35250583, 2022). "Collectively, these observations are consistent with the hypothesis that augmented GH signaling in CBK hearts, possibly via enhanced local IGF1 action, contributes towards cardiomyopathy development." (PMID 35250583, 2022). "IGF-1 is considered to be a protective factor for the heart, especially in cardiomyopathy." (PMID 35282347, 2022). "Elevated levels of IGF-1 and GH may lead to cardiomyopathy in three ways: myocyte growth and structure, cardiac contractility, and vascular function." (PMID 31741320, 2020). "The CTD database showed that the common hub genes (IGF1, MYH11, TGFB3, ALB, and AGT) were targets in cardiomyopathies." (PMID 35845066, 2022). "Among the identified DEGs, IGF1, MYH11, and TGFB3 had a high degree of interaction in the PPI network and were predicted to be key genes in cardiomyopathy." (PMID 35845066, 2022). "In the same line, treatment of rats with IGF-1 protects from cardiomyopathy induced by DOX, and expression of IGF-1 and its receptor is increased in rat hearts following physical exercise." (PMID 21084725, 2010). "They found that cyanocobalamin could prevent and reverse cardiomyopathy by adequately restoring DNMT function, leading to reduced transcription of SOCS1/3 and production of insulin-like growth factor-1 (IGF-1)." (PMID 37947606, 2023). "This slight increase in COL1A2 and IGF1 in ADAR2-/- mouse heart tissues indicated that ADAR2 is not the core factor related to cardiomyopathy." (PMID 31039163, 2019).